TGFB1 (transforming growth factor beta 1)
Diseases named in the same sentence as TGFB1 in open-access papers (continued):
Sharing a sentence is not in itself a finding about the gene and the disease.
tumor (continued). "Compared with young patients with a tumor, we found that the epithelial subset cE03 showed elevated FUT2 and FUT3 and coexpression with tumor-promoting TGFB1 and interleukin 6 cytokine family signal transducer (IL6ST) gene expression in older patients with a tumor." (PMID 38456503, 2024). "In this respect, treatment with MRS1220 reduced the transcripts of 29 genes that could tentatively favor the tumor phenotype; three targets that promote chemoresistance, LIMD1, TRIB2, and TGFB1, were distinguished." (PMID 38794149, 2024). "Additionally, older patients with a tumor exhibited elevated FUT2, FUT3, and FUT8 coexpression with tumor-promoting IL6ST, IL22RA1, TGFB1, and TGFBR1 genes compared with young tumor." (PMID 38456503, 2024). "Additionally, a differential expression of the cytokine genes CCL2, CCL20, TGFB1, and TGFB2; the transcription factor gene IRF4; and the receptor genes CCR2, IL10RB, TGFBR1, and TGFBR2 was identified in tumor tissue and vestibular nerve tissue." (PMID 39272860, 2024). "Macrophages could be polarized to the tumor growth-promoting M2 subtype in the tumor environment by cytokines, such as CCL2, CCL5, CCL18, and TGFB1 and the mRNA levels of the transcription factor IRF4." (PMID 39272860, 2024). "High expression levels of TGF-β ligand TGFB1 and its receptor TGFBR2, two crucial genes of the TGF-β signaling pathway, are associated with non-response and decreased OS in tumor patients treated with ICI immunotherapy." (PMID 38524135, 2024). "Notably, tumor samples from DIPG patients expressed significantly higher levels of TGFB2 mRNA than control pons samples, but the TGFB1, as well as TGFB3 mRNA levels in DIPG samples were significantly lower than in the control pons samples." (PMID 36980562, 2023). "We obtained similar results in an independent validation dataset of microarray-based mRNA levels for TGFB1, TGFB2, and TGFB3, and their correlated expression with specific transcription factors in tumor specimens from 41 pediatric patients with DIPG (N = 29) or H3K27M-mutant GBM." (PMID 36980562, 2023). "The TGFβ1 gene expression is higher in the tumor tissues of non-responders following anti-PD-1/PD-L1 treatments." (PMID 36874133, 2023). "In addition, we examined the expression levels of PD1, PDL1, CTLA4, TGFB1, TIGIT, IDO1, and LAG3 in 51 tumor samples." (PMID 37928532, 2023). "Notably, macrophages that received lncARSR delivered by tumor cells demonstrated a significant increase in CD163 and CD206 expression, along with a rise in anti-inflammatory cytokines TGFβ-1 and IL-10 secreted by macrophages." (PMID 37469514, 2023). "This is in line with recent reports demonstrating a tumor inhibitory capacity of PRELP, which might be at least partially due to its ability to directly bind TGFB1." (PMID 37730606, 2023). "Moreover, we found that expression levels of IL10, TGFβ1 and FOXP3 in tumour B cells from untreated CLL B patients were predictive of disease progression." (PMID 36973425, 2023). "Consequently, these macrophages enhance tumor progression and metastasis by secreting high amounts of chemokine (C-C motif) ligand 18 (CCL18) and transforming growth factor beta 1 (TGFβ1)." (PMID 37190141, 2023). "Similar results were obtained in an independent validation dataset of microarray-based mRNA levels for TGFB1, TGFB2, and TGFB3, and their correlated expression with specific transcription factors in tumor specimens from 41 pediatric patients with DIPG (n = 29) or H3K27M-mutant GBM." (PMID 36980562, 2023). "Myofibroblasts produced by soluble TGFβ1 do not exhibit characteristics that promote tumor growth or angiogenesis." (PMID 38202898, 2023).
tumor (continued). "Then, TGFβ1 binds to TGFBR1/R2 in tumor cells to activate Smad2/3 signalling to increase the expression of PAI-1, which further activates PI3K/AKTThr308, p-Bad and Bcl-2 to support tumor cell survival in circulation." (PMID 37705745, 2023). "Furthermore, exogenous TGFβ1 also increased the levels of these three subunits in neutrophils, suggesting that tumor cells up-regulate ITGA6, ITGB1 and ITGB4 in neutrophils through TGFβ1 regulation." (PMID 37056931, 2023). "PD-L1, TGFB1, IL10, and IL13 are primary effectors for immunosuppressive tumor microenvironment." (PMID 36906597, 2023). "Because we found that NDRG1 and its phosphorylation at Thr346 were altered by TGFβ1, we next tested whether their expression levels were correlated in TNBC patient tumor tissue." (PMID 36594086, 2023). "It has also been shown that IgG1 isotype control does not affect TGFβ1 protein expression in PD-L1 high tumor cells." (PMID 38152616, 2023). "Notably, Twist, which was consistently inhibited by NDRG1 knockdown in presence of TGFβ1, is not only involved in EMT and metastasis but leads to the generation of cancer stem cells (CSCs), chemoresistance, and tumor progression." (PMID 36594086, 2023). "For instance, NK-derived exosomes carrying the tumor-suppressive miRNA-186 exhibited cytotoxicity against MYCN-amplified neuroblastoma cells, where miRNA-186 inhibited MYCN and exempted cancer cells from TGFβ1-dependent immune escape." (PMID 36119094, 2022). "This suggests that the M cells underwent MET in vivo as the M tumours grew deprived of a persistent TGFβ1 stimulus, unlike the M cells grown in vitro." (PMID 36101425, 2022). "Three isoforms of TGFβ (TGFβ 1, TGFβ 2, and TGFβ 3) instigate cellular phenotypical changes through canonical (SMAD) and non-canonical (MAPK, JAK/STAT, and PI3K/Akt) signalling pathways that mediate its role both as a tumour suppressor and a tumour promoter." (PMID 35681586, 2022). "What is more, equally important observation in the study was related to the high relative expression levels of the TGFB1 gene expression in neoplasms without blood vessel involvement." (PMID 35798776, 2022). "Analysis of GFP-positive stromal cells isolated by fluorescence-activated cell sorting (FACS) showed reduced Sqstm1 (coding for p62) mRNA levels in stromal cells on incubation with tumor cells, which also correlated with an increase in bona fide CAF markers, such as Tgfb1 and Sdf-1." (PMID 35545049, 2022). "Interestingly, NicheNet analysis predicted TGFB1 as the most highly ranked ligand expressed by angiogenic ECs, that likely affects the differential transcriptome in myeloid cells, indicating that TGFB1 might indeed be active in modulating myeloid cells, and possibly TAMs, in the tumor." (PMID 36127427, 2022). "Although cFOS is elevated but not statistically significant, our TGFβ1 results reveal statistically significant overexpression in respective cytosolic extracts, which was proportional to the size of respective mALN tumor deposits." (PMID 35658894, 2022). "However, this was accompanied by significantly higher TGFB1 levels and unchanged IL17 levels, despite evidence of increased Th17 cell recruitment in CDH17 high versus low-methylation tumours." (PMID 36612154, 2022). "Higher transforming growth factor-beta 1 (TGF-β1) is found both in plasma and tumor tissues of JORRP, and anti-TGF-β1 antibody could restore NK cell cytolytic activity and upregulate NKp30 and NKG2D expression." (PMID 35350785, 2022). "Furthermore, fibrogenic factors, including PDGFRβ, CXCR4, and TGFB1, which may be expressed by the stromal cells or the reprogrammed brain cells, can potentiate fibrosis in the metastasis brain environment which, in turn, contributes to increased angiogenesis and tumor growth." (PMID 36216799, 2022). "qRT-PCR analysis of bulk tumor RNA indicated that ACT+MS-275 treatment downregulated ARG1, NOS2, and TGFB1 expression, which may prohibit Treg expansion." (PMID 35972798, 2022).
tumor (continued). "In conclusion, this study revealed that KD alleviated RILF through the regulation of TGFβ1/Smad/CTGF pathway with no side effects on the tumor therapy." (PMID 35126163, 2022). "Several growth factors secreted by tumor cells, such as PDGF-B, VEGF-A, and TGFβ-1, may trigger the prevalence of a PDGFRβ+/desmin+ pericyte phenotype through the acquisition of αSMA, RGS5, NG2, and desmin immunopositivity in activated pericytes at BCBM sites." (PMID 35455945, 2022). "The tumor immune estimation resource (TIMER) platform was applied to explore the correlation between infiltration levels of immune cells and the expression of four prognosis-related genes (including NR6A1, CXCL5, TGFB1, and C3)." (PMID 36071851, 2022). "Upon analyzing the functional state of the tumor-infiltrating Tregs, we observed that Tregs in B7x+ tumors had greater expression of TGF-LAP, a surface marker of TGFβ1 production, suggesting that these cells had greater suppressive capacity than their counterparts in B7x− tumors." (PMID 35523809, 2022). "We then analyzed the associations between CXCL2 expression and classical macrophage phenotype markers of M0 (undifferentiated) (AIF1), M1 (anti-tumor) (IL12A, TNF, NOS2, PTGS2) and M2 (tumor-promoting) (IL10, CD163, TGFB1, CSF1R) in TCGA-LIHC cohort with Spearman’s rank correlation test." (PMID 36276119, 2022). "Numerous cytokines and chemokines known to enhance stromal activity such as TGFB1, TGFB2, TGFB3, CXCL12, CCL2 and IL-6 were found downregulated in 211F MEF cells, suggesting a potential tumor-promoting function of Y211 phosphorylation through regulation of the secretome in the stromal environment." (PMID 35628489, 2022). "In contrast, the PLAUR and TGFB1 proteins were expressed in tumor cells, but only at a very weak level (data not shown)." (PMID 36425786, 2022). "Therefore, these six tumor-related genes (ITGA5, PLAU, PLAUR, SERPINE1, TGFB1, and VEGFC) were considered as prognostic biomarkers for HNSCC." (PMID 36425786, 2022). "Moreover, tumor cell growth is blocked by NEX containing the tumor suppressor miR-186, and these NEX also derepress TGFβ1-dependent inhibition of NK cells." (PMID 36591444, 2022). "On the other hand, the aberrant TGFβ1 mRNA level correlates with prolonged disease-free survival with no regard to the tumor stage, grade, size, subtype (endometrioid-type vs. clear-cell carcinoma), myometrial invasion, lymphovascular invasion, and recurrence." (PMID 34501347, 2021). "Both tumor cell lines, LLC1.1 and MC-38, produce significant amounts of Tgfβ1." (PMID 34868988, 2021). "Moreover, the positive correlations between CCDC137 expression and immunosuppressive genes, such as TGFB1, NECTIN2, LGALS9, LAG3, and IL10RB, indicate the key role of CCDC137 in regulating tumor immunology, macrophage polarization, and CAFs formation." (PMID 34055889, 2021). "Transforming growth factor-beta 1 (TGF-β1), a pro-fibrotic tumour-derived factor promotes fibroblast differentiation in the tumour microenvironment and is thought to contribute to the development of pro-tumourigenic cancer-associated fibroblasts (CAFs) by promoting myofibroblast differentiation." (PMID 34762649, 2021). "It is possible that Th17 is promoted in the presence of increased TGFB1 with non-diminished IL6 or that Th17 infiltrates to the tumor, upon which the tumor microenvironment promotes memory differentiation." (PMID 34307352, 2021). "Furthermore, dendritic cells exposed to MUC2 produce less TNFα and IL-12, as well as more IL-10 and TGFβ1 in the large intestine, which suggests that MUC2 can deliver immunoregulatory signals to support tumor growth and treatment resistance." (PMID 34300195, 2021). "These inflammatory CAFs release factors, such as TGFβ-1, C-X-C motif chemokine ligand 12 (CXCL12), PDGF and IL-6, that enhanced tumor cell dispersion, scattering, and migration, by stimulating the chemokine receptors CCR2, CCR5, and CXCR1/2 and Ras-activating receptors, expressed by BC cells." (PMID 34885027, 2021).
tumor (continued). "To test whether these events might contribute to TGFβ induced accelerated c-Myc HCC progression, we first examined the changes of tumor related immune milieu in EGFP and TGFβ1 expressing c-Myc liver tumors." (PMID 33608500, 2021). "Considering the limited tumor nodules in c-Myc/TGFβ1 HCC model, one plausible explanation is that a small percentage of c-Myc injected hepatocytes were able to induce the expression of these anti-apoptotic genes, thus escaping TGFβ1 induced apoptosis." (PMID 33608500, 2021). "In both LUAD and LUSC tumour digests, not only are peritumoral CD90+CD73+ cells enriched in the ECM/stromal gene signature, which was amplified by TGFβ1, but these cells themselves are a major source of inflammatory-driven TGFβ1 secretion." (PMID 34740105, 2021). "We use freshly resected tumor material from NSCLC patients to show that mesenchymal cells within the TME marked by CD90 and CD73 are enriched in the ECM/stromal gene signature amplified by TGFβ1 and are potently immunosuppressive." (PMID 34740105, 2021). "In tumours resected from a separate cohort of NSCLC patients, we identified CD90+CD73+ peritumoral cells that were enriched in the ECM/stromal gene signature, which was amplified by TGFβ1." (PMID 34740105, 2021). "SCF, TGFβ1, and PCNA-positive staining was widely observed in these tumor tissues." (PMID 34884420, 2021). "Mechanistically, tranilast facilitated ECM remodeling by reducing TGFβ1 expression, thereby inhibiting Smad2/3 phosphorylation, and suppressing TGFβ-mediated expression of COL1A1, connective tissue growth factor (CTGF), and hyaluronan synthase 2 (HAS2) in MCF10CA1a tumor xenografts." (PMID 33391538, 2021). "In CT26 isoform-specific inhibition with TGFβ1 and pan-TGFβ inhibition were effective at delaying tumor growth while TGFβ3 inhibition had no anti-tumor effect." (PMID 34789823, 2021). "The results were consistent with in vitro analyses showing that overexpression of TGFβ1 does not significantly affect tumor growth." (PMID 33608500, 2021). "After anti-PD-1/PD-L1 treatments, the TGFB1 gene expression is higher in the non-responder’s tumor tissues." (PMID 33593403, 2021). "TGFβ1 and EMT are key regulators of tumor cell migration, invasion, and metastasis." (PMID 34906074, 2021). "Of note, liver tumor nodules were detected as early as 4 weeks after tumor cell implantation in the TGFβ1 group, whereas no tumor was detected in the control group." (PMID 33608500, 2021). "TGFB1, IL1B, IL10, IL6, PTGS2, and PPARG closely interacted with the tumor microenvironment." (PMID 34394377, 2021). "Predictors of poor outcomes included having tumours (P = 0.0193) and having a chronic onset (P = 0.0306), and predictors of relapses included having lower levels of CSF BAFF (P = 0.0491) and having a larger ratio of serum TGFβ1/serum CXCL13 (P = 0.0182)." (PMID 34872566, 2021). "In fact, two key TGF-β pathway genes, TGFB1, a TGF-β ligand, and TGFBR2, a TGF-β receptor, were found to have increased expression in tumor samples of non-responders, and to be associated with reduced OS." (PMID 34830879, 2021). "In contrast, upon exposure to IL-4, IL-10, and IL-13, transforming growth factor beta 1 (TGFβ1), and prostaglandin E2 (PGE2), macrophages can undergo M2 activation, which is characterized by tissue repair, matrix remodeling, and tumor promotion, and mirrors those of Th2 responses." (PMID 34300195, 2021). "Later, Thomas and Massague generated EL4 cells expressing a short hairpin RNA (shRNA) targeting Tgfb1 and showed that the cellular source of TGF-β1 blocking anti-tumor T cells is not tumor cells." (PMID 34302795, 2021). "Moreover, the positive correlation between FOXD1 expression and immunosuppressive genes, such as PD-L1, IL-10, TGFB1 and TGFBR1, indicate the key role of FOXD1 in regulating tumor immunology." (PMID 34028536, 2021).
tumor (continued). "For example, four growth factors (TGFB1, HGF, BMP1 and PDGFB) that are well-known to induce EMT, exhibited higher expression levels in CD4/8+ T cells compared with other immune and tumor cells, suggesting that anti-immune evasion promotes EMT as well by producing growth factors which induce EMT." (PMID 34158591, 2021). "Additionally, in mucoepidermoid carcinoma, TGFB1 was overexpressed on ECs and, of note, TGFRB2 was inversely proportional to tumor grade: low-grade tumors overexpressed TGFRBII, whereas neither high-grade tumor showed TGFRBII expression." (PMID 34940041, 2021). "The immunomodulatory factors SerpinE1, TGFβ1, CXCL1 and CXCL12 act directly on immune cells to induce a wound-healing phenotype that contributes to angiogenesis, epithelial-to-mesenchymal transition (EMT), tumour growth and metastasis." (PMID 34885111, 2021). "Moreover, cytokines and growth factors such as TGFB1, IL‐6 and IL‐17D can increase the interplay between MDSC and Th17 cells in tumor microenvironment." (PMID 33107145, 2021). "Furthermore, the administration of BMSCs-TGFβ-1 cells in the MHCC97-H and MHCC97-L xenograft mouse model inhibited tumor growth." (PMID 34249257, 2021). "Importantly, the positive correlations between FUCA2 expression and immunosuppressive genes, such as TGFB1, PD-L1, and IL10, further affirming the key role played by FUCA2 in regulation of tumor immunology, and macrophage polarization." (PMID 34745134, 2021). "The comparative genomic loci of most human and mouse TGFβ axis genes, including TGFB1–3, TGFBR1–3, and TGFBI, were mapped ~20 years ago, which paved the way for numerous functional studies of individual TGFβ genes in tumor biology." (PMID 32605311, 2020). "We found that the TGFB1 is highly expressed in Hugo cohort rather than van Allen cohort (Wilcoxon test, P=0.04), which indicated that the tumor microenvironment differences should be considered in these two cohorts." (PMID 32697765, 2020). "Also, the human PSCs were activated by the co-cultured mouse tumour cells as indicated by increased ACTA2, COL1A1, FN and TGFB1 mRNA levels." (PMID 32460715, 2020). "RT‐qPCR results showed that, compared with the xenograft tumor zebrafish model group, FH could significantly reduce Snail2, ZEB2, TWIST1, and TGFβ1 mRNA expression (P < .01, 0.05)." (PMID 32037729, 2020). "Moreover, expression changes in CD105, TGFβ1, VEGF, HIF-1a and tumor vasculature in the presence of low and high doses of bevacizumab in nude mouse models and clinical specimens require further elucidation." (PMID 32587778, 2020). "Both TGFβ1 and GDF15 belongs to TGF-β superfamily, TGFβ1 was reported to activate SREBP2 in kidney mesangial cells, SREBF2 activation was dependent on SCAP, SCAP or SREBPs promoted tumor progression in various cancer." (PMID 33123476, 2020). "Regardless of the tumor type or tumor site, Ly6c1high CAFs (iCAFs) showed enrichment for Il33, Il6, Ccl7, Cxcl1 and Cxcl12 whereas α-SMAhigh CAFs (myCAFs) expressed high levels of Tgfb1, Tgfb2 and Ctgf." (PMID 32455670, 2020). "Smaller tumour size and negative association with TGFB1, CDH2 and LLGL2 strengthen the tumour suppressive role of KANK1." (PMID 31679074, 2020). "Moreover, the immune checkpoints B7-H3/CD276 and OX40 were found to be significantly co-expressed with core EMT genes, TGFB1, CXCR4, IL10, and IL6 on tumor microenvironment as vascular endothelial and myeloid cells." (PMID 32708431, 2020). "Notably, TCGA data showed higher HIF1A and TGFB1 gene expression in HCC tissues and its correlation with the overall survival rate, tumor cell proliferation and EMT." (PMID 31819036, 2019). "When VX2 cells and MSCs were co-inoculated in group control 1, the ROD values of TGFβ1 and EGF were both significantly increased (0.899±0.124, 1.053±0.107), which indicated that MSCs facilitated the expression of these two growth factors in VX2 tumor tissue." (PMID 31528217, 2019).